RNF103-CHMP3 (RNF103-CHMP3 readthrough)
Synonyms: RNF103-VPS24
Gene: Protein-coding gene on chromosome 2 (86,505,668 to 86,721,122, reverse strand). Ensembl gene ENSG00000249884.
Genetic constraint (gnomAD): Loss-of-function variants: 12 observed, 27.08 expected, observed/expected ratio (o/e) 0.44, 90% interval 0.28 to 0.72. The upper end of that interval is the gene's LOEUF score, 0.72, which puts it in group 2 of 6, group 1 being the genes least tolerant of losing a copy. Missense variants: 238 observed, 303.38 expected, observed/expected ratio (o/e) 0.78, 90% interval 0.7 to 0.87. Synonymous variants: 91 observed, 96.56 expected, observed/expected ratio (o/e) 0.94, 90% interval 0.79 to 1.12.